HMGB1 (high mobility group box 1)
Diseases named in the same sentence as HMGB1 in open-access papers (continued):
Sharing a sentence is not in itself a finding about the gene and the disease.
asthma (62 papers, 2011 to 2025). "The levels of HMGB-1 were significantly elevated in rheumatoid arthritis patients during the active phase and were also associated with asthma severity." (PMID 39416736, 2024). "HMGB1 is known to play a pathogenic role in asthma with contributions to airway smooth muscle (ASM) dysfunction and airway reactivity." (PMID 30728013, 2019). "Recent studies indicate that activation of HMGB1 signaling is associated with acute lung injury, asthma, pulmonary fibrosis, and other respiratory diseases and HMGB1 expression is correlated with respiratory disease severity." (PMID 28337225, 2017). "This review aim is to analyse advances on HMGB1 role, employment and potential diagnostic application in asthma." (PMID 28630596, 2017). "Increased levels of HMGB1 have been detected in the sputum of patients with asthma and high levels of HMGB1 have been associated with reduced lung function." (PMID 28099113, 2017). "This literature review aims to analyse advances on HMGB1 role, employment and potential diagnostic application in asthma." (PMID 28630596, 2017). "Increased abundance of HMGB1 is associated with several pathological disorders such as cancer, asthma and chronic obstructive pulmonary disease (COPD)." (PMID 25726846, 2015). "In particular, patients identified by higher Asthma Control Questionnaire (ACQ) results expressed significantly higher neutrophil numbers that were associated with elevated HMGB1 and RAGE expression." (PMID 25359169, 2014). "In the same study, higher levels of HMGB1 protein and esRAGE have been observed in asthmatic sputum, but only increased levels of HMGB1 were found to be associated with severity of asthma." (PMID 24102034, 2013). "In recent years, increasing studies suggest that HMGB1 may cause cell damage and mediate inflammatory response in lung tissue of patients with asthma." (PMID 38156383, 2023). "Collectively, these results indicate that RSV-induced HMGB1 release enhances the type 2 response and the secretion of proinflammatory mediators and is associated with an elevated viral load, airway smooth muscle remodeling, and a higher risk of asthma." (PMID 37798799, 2023). "The HMGB-1 level is also associated with the severity of asthma and neutrophils in sputum." (PMID 35626330, 2022). "The major cellular contributors of multiple asthma-associated inflammatory mediators, such as Il33, Hmgb1, Retnla, and Ager were identified, and a cluster of novel allergy-associated molecules, such as Chia1, Nnat, and Nr4a1 were found in different lung epithelial cells." (PMID 35627266, 2022). "Neutralizing HMGB1 can attenuate asthma-associated airway remodeling and inflammation." (PMID 31958320, 2020). "A total of 19 studies assessing the association between HMGB1 and asthma were identified." (PMID 28630596, 2017). "Interestingly, several of the viruses and bacteria that have been implicated in the pathogenesis of asthma are also known to induce HMGB1." (PMID 28099113, 2017). "To investigate this, we treated IRF7-/- mice with anti-HMGB1 (clone 2G7), which neutralises both all-thiol and disulphide HMGB1, or an isotype-matched control, then killed the mice at 10 dpi when the pathologies associated with asthma onset were most prominent." (PMID 32658914, 2020). "Therefore, we next assessed whether neutralising HMGB1 would protect RAGE deficient mice from developing the features of asthma following re-infection with PVM." (PMID 28099113, 2017). "In a mouse model of diisononyl phthalate (DINP)-induced asthma, lung tissue was analyzed along with bronchial alveolar lavage fluid, following anti-HMGB1 treatment, which inhibited HMGB1 expression and visibly reduced inflammatory infiltration in the airways." (PMID 40723867, 2025). "The level of HMGB1 in sputum, plasma, and serum in people with asthma is significantly elevated compared to people with healthy asthma." (PMID 40723867, 2025).
asthma (continued). "A study conducted on human airway smooth muscle cells showed that the use of astragaloside IV (ASIV) to treat asthma significantly affects HMGB1 by weakening the expression of this protein and thus preventing its entry into the cytoplasm." (PMID 40723867, 2025). "The detailed mechanism of action of HMGB1 in the pathophysiology of asthma is not yet well understood." (PMID 40723867, 2025). "Previous studies have shown that miR‐140‐3p can modulate the JAK2/STAT3 signaling by targeting HMGB1, reducing airway inflammation and remodeling in asthma." (PMID 40044625, 2025). "Another study revealed HMGB-1 levels between patients with asthma and healthy subjects; the levels were significantly higher in patients with asthma." (PMID 39416736, 2024). "circVPS33A targeted miR-192-5p to upregulate the expression of high-mobility group box 1 (HMGB1), a strong pro-inflammatory mediator in the pathogenesis of asthma, leading to lung injury." (PMID 38601461, 2024). "Research has shown that prophylactic or therapeutic administration of P2Y13-R, also known as IL-33 and High-mobility group box1 (HMGB1)’s novel gatekeeper, in experimental asthma models can attenuate the onset and progression of asthma." (PMID 39301028, 2024). "In the murine asthma model study, HMGB1 has been confirmed to directly and indirectly induce Th17 immune response by TLR4‐NF‐κB signal pathway." (PMID 38414294, 2024). "Elevated levels of many DAMPs, including HMGB1, were reported in induced serum and sputum of patients with asthma and COPD in many studies." (PMID 36830972, 2023). "While inhibition of HMGB1 reduces the lung inflammatory cell infiltration, goblet cell proliferation, and airway mucus production to improve asthma." (PMID 38156383, 2023). "Meanwhile, it is reported that HMGB1 promotes and induces asthma through immune system, secretion of enzyme‐promoting inflammatory factors, and signal transduction." (PMID 38156383, 2023). "HMGB1 is a therapeutic target of asthma, but more research works are needed to investigate the role of HMGB1 in asthma and its mechanism in future." (PMID 38156383, 2023). "Although there is evidence that HMGB1 protein plays an important role in the pathogenesis of asthma, the specific expression and distribution of HMGB1 protein in the airway and lungs have not been conclusive." (PMID 38156383, 2023). "Clinical studies have revealed that higher levels of HMGB1 correlate with the clinical severity of RSV-induced bronchiolitis and act as an independent risk factor for children to develop asthma during follow-up." (PMID 37798799, 2023). "HMGB1 levels in patients with asthma and COPD reported a positive correlation with neutrophil counts and percentage of neutrophils." (PMID 36830972, 2023). "This study confirmed the significant role of IL-33 and HMGB1 in neutrophilic asthma and suggested that Lip-1 reduced asthma by blocking ferroptosis." (PMID 36675299, 2023). "Several experiments have shown a correlation between asthma, IL-33, non-coding genetic material, and HMGB1." (PMID 36675299, 2023). "Previous studies have reported that blood levels of HMGB1 are higher in depressed patients with asthma, and that patients with high blood levels of HMGB1 during acute cerebral infarction are more likely to experience a depressive state 3 months later." (PMID 37337402, 2023). "In asthma, HMGB1 expression induces HSP expression through the TLR4 / MYD88 / NF-kB pathway, which eventually produces IL-4 and IL-13." (PMID 37422662, 2023). "The main role played by the HMGB1 and IL-33 axis has also been theorised in other experimental models of asthma, such as aspirin-exacerbated respiratory disease (AERD)." (PMID 36675299, 2023). "Immunofluorescent staining of bronchial biopsies revealed that the expression of RUNX2 and HMGB1 were both increased in the epithelial cells of asthma patients compared to controls." (PMID 35093061, 2022).
asthma (continued). "HMGB1 transcript levels in bronchial brushings were significantly up-regulated in asthma patients compared to control subjects." (PMID 35093061, 2022). "Combining all these genes with the same directions of changes in EpCAM+ cells, AT2 cells, AP, BAS, and ciliated cells, there was significant enrichment for NRF2-mediated Oxidative Stress Response, HMGB1 Signaling and Airway Inflammation in Asthma." (PMID 35627266, 2022). "Several asthma-related genes were identified: detoxification enzymes (Cyp2a5, Gsto1, Gstp1, Gstm1, and Aldh1a1) were downregulated while Hmgb1 (alarmin) was upregulated." (PMID 35627266, 2022). "Epithelial mesenchymal transition (EMT) is implicated in bronchial remodeling in asthma and chronic obstructive pulmonary disease (COPD), and HMGB1 can induce EMT in human airway epithelial cells." (PMID 36741411, 2022). "In animal models of asthma, airway eosinophilic inflammation was ameliorated by blocking HMGB1 activity." (PMID 35093061, 2022). "In patients with asthma, the sputum HMGB-1 level is increased and inversely correlated with the percentage predicted forced expiratory volume in 1 s (%FEV1) and FEV1/forced vital capacity (FVC) ratio." (PMID 35626330, 2022). "RUNX2 and HMGB1 expression was both enhanced in airway epithelium and was correlated with each other in asthma patients." (PMID 35093061, 2022). "Recently, it has been reported that RSV infection contributes to the onset of asthma in later life by inducing High Mobility Group Box-1 (HMGB1), as a result of necroptosis, a programmed cell death of airway epithelial cells." (PMID 36204661, 2022). "We demonstrated that, like RUNX2, HMGB1 expression was increased in bronchial epithelium of asthma patients, IL‐13‐stimulated human bronchial epithelial cells and OVA‐challenged mice airways." (PMID 35093061, 2022). "Taken together, in HDM-induced asthma, HMGB1 signaling pathway is activated, resulting in airway inflammation and apoptosis." (PMID 33541260, 2021). "Not only CS can induce DAMP release, as ovalbumin-sensitized mice display increased HMGB1 expression, but also the addition of exogenous HMGB1 increases Th2 cells and asthma-related cytokines such as IL-4 and IL-17." (PMID 34248677, 2021). "In this study, using cultured cells and a HDM-induced murine asthma model, we investigated the participation of HMGB1 together with potential signaling molecules in progression to airway inflammation of asthma." (PMID 33541260, 2021). "Studies have shown that the HMGB1/TLR4 signaling pathway is abnormally activated in mouse models such as asthma and allergic rhinitis." (PMID 34007295, 2021). "The effect of evodiamine treatment protects the asthma, as evodiamine reduces airway inflammation and remodelling in the lung tissue by downregulating the HMGB1/NF-κB/TLR-4 pathway in asthma." (PMID 33577738, 2021). "This study was aimed to clarify the protective roles of CC16 on airway epithelia in HDM-induced asthma and the regulation of HMGB1 by CC16." (PMID 33541260, 2021). "Overall, these data demonstrated that HMGB1-mediated airway epithelial cell apoptosis was correlated with TLR4/NF-κB signaling activation in the in vitro model of HDM-induced asthma." (PMID 33541260, 2021). "For example, interference with the HMGB1/TLR4 signaling pathway suppresses airway inflammation in asthma." (PMID 34007295, 2021). "Lower levels of TLR-4, MyD88, NF-κB, and HMGB1 mRNA in lung tissue were measured in the evodiamine-treated group than in the asthma group." (PMID 33577738, 2021). "Apart from cancer, HMGB1 is also involved in asthma pathogenesis as HMGB1 and its receptor RAGE are overexpressed in the sputum of severe asthma patients." (PMID 34305932, 2021). "It has been reported that HMGB1 critically participates in inflammatory development of asthma by acting as a ligand of TLR4." (PMID 33541260, 2021). "HMGB1 is upregulated in the airways in asthma and potentiates airway smooth muscle contraction via TLR4." (PMID 33925132, 2021).
asthma (continued). "Pharmacological neutralizing HMGB1 was found to suppress asthma-related inflammation and airway remodeling." (PMID 33541260, 2021). "Sputum HMGB1 is increased in asthmatic children and correlates with asthma severity and inversely with lung function indices." (PMID 33925132, 2021). "Together, our findings uncover an important role for HMGB1 in ILC2 activation and implicate ILC2s as important effectors of both type-2 inflammation and ASM thickening in early-life, predisposing to later asthma." (PMID 32658914, 2020). "MiR-19 mediated HMGB1-induced proliferation and migration of human airway smooth muscle cells to affect the airway remodeling in asthma by targeting PTEN." (PMID 32065213, 2020). "It has been found that HMGB1 is associated with increased airway smooth muscle contraction and TLR4 activation in asthma." (PMID 31958320, 2020). "Taken together with our previous findings, and reports from other groups, it is increasingly apparent that HMGB1 is an important mediator in the pathogenesis of viral bronchiolitis and asthma." (PMID 32658914, 2020). "The airway epithelium has been shown to be a primary source of abnormal HMGB1 expression in chronic airway disease, driving progressive inflammation in asthma and chronic obstructive pulmonary disease." (PMID 31958320, 2020). "Collectively, our findings provide a mechanistic basis to explain the effectiveness of anti-HMGB1 treatment or RAGE deficiency in acute and chronic models of allergen- and viral-induced experimental asthma." (PMID 32658914, 2020). "Next, increased expression of HMGB1 in the lung ASM observed in our study assumes importance since it is known to contribute to ASM dysfunction in a human asthma model." (PMID 30728013, 2019). "Compared to NS and HS (1.62 ± 0.27 and 1.59 ± 0.27 ng/mL, respectively), the HMGB1 levels in the induced sputum were significantly higher in patients with asthma, COPD, and ACO (4.51 ± 0.39, 15.77 ± 1.32, and 13.59 ± 1.22 ng/mL, respectively)." (PMID 31848359, 2019). "The elevated levels of HMGB1 in ACO suggested its role in the pathogenesis of ACO as well as asthma and COPD." (PMID 31848359, 2019). "In a previous study, we also demonstrated that treatment with anti-HMGB1 antibody significantly reversed the development of airway remodeling in a murine asthma model." (PMID 31848359, 2019). "Sputum HMGB1 had a high AUC of the ROC curve while distinguishing ACO patients from asthma patients." (PMID 31848359, 2019). "Levels of HMGB1 were significantly higher in TDI induced murine asthma model and EP treatment down-regulated HMGB1 in a dose-dependent manner." (PMID 28630596, 2017). "In induced sputum samples of asthma group was detected an augmented presence of neutrophils, HMGB1 and RAGE levels." (PMID 28630596, 2017). "HMGB1 levels in induced sputum were higher in patients with all severities of asthma and in those with COPD than healthy subjects." (PMID 28630596, 2017). "Level serum IgE was significantly increased in TDI-induced murine asthma model, as well as IL-4 in supernatant of cultured lymphocytes, the number of inflammatory cells and the protein level of HMGB1 in BAL fluid and lung tissue." (PMID 28630596, 2017). "Plasma and sputum HMGB1 levels were higher in patients with severe asthma than in patients with mild one." (PMID 28630596, 2017). "In order to improve knowledge of the disease have been discovered new biomarkers of airway inflammation and respiratory diseases such as asthma, including HMGB1." (PMID 28630596, 2017). "They showed that sputum HMGB1 levels were significantly augmented in patients with asthma compared to healthy ones." (PMID 28630596, 2017). "We reviewed experimental studies that investigated the pathogenetic role of HMGB in bronchial airway hyper-responsiveness, inflammation and the correlation between HMGB1 level and asthma." (PMID 28630596, 2017).
asthma (continued). "On the other hand animals studies also demonstrated that treating asthma with drugs known to lower HMGB-1 levels or with anti-HMGB-1 antibodies ameliorate animals condition and decrease in situ inflammatory markers." (PMID 28630596, 2017). "Particularly, patients with severe asthma presented higher sputum HMGB1 levels than patients with mild asthma and than moderate asthmatic ones." (PMID 28630596, 2017). "Collectively, these findings and others highlight a central role for HMGB1 in the pathogenesis of multiple subtypes of asthma." (PMID 28099113, 2017). "Plasma HMGB1 levels were noticeably higher in patients with moderate asthma than in those with mild asthma." (PMID 28630596, 2017). "In TDI-induced asthma, ethyl pyruvate reduced the expression and release of HMGB1, which was in line with obvious improvement in neutrophil infiltration into the airway." (PMID 27026909, 2016). "Previous studies showed that HMGB1 is involved in the pathologic mechanism of pulmonary fibrosis-related diseases such as asthma, COPD, cystic fibrosis airway disease, and idiopathic pulmonary fibrosis." (PMID 25692286, 2015). "HMGB1 has been shown to be elevated in sputum of asthma and COPD patients 7,22 and increased serum levels of HMGB1 were measured in IPAH patients." (PMID 25726846, 2015). "Increased levels of HMGB1 in the sputum or bronchoalveolar lavage fluid of asthma, chronic obstructive pulmonary disease (COPD), systemic sclerosis and idiopathic pulmonary fibrosis patients are associated with disease severity 4–8." (PMID 25726846, 2015). "A previous study showed that the concentration of HMGB1 in bronchial alveolar lavage fluid in healthy controls, asthma, and COPD patents was 3.7, 6.3, and 20 ng/mL, respectively." (PMID 25692286, 2015). "Plasma HMGB1 levels were similar to the ones obtained in sputum for exception of patients with mild asthma, in which levels were normal." (PMID 26798204, 2015). "It was found that asthma group mice developed a significant increase in HMGB1 expression compared with control group mice (P < 0.01)." (PMID 24959003, 2014). "As expected, the administration of anti-HMGB1 IgG significantly downregulated the number of Th17 cells in lung tissue (P < 0.05 versus the Asthma group or IgG group)." (PMID 24959003, 2014). "Because the level of IL-17A in BALF was increased in the asthma group mice and anti-HMGB1 IgG treatment suppressed it, we examined the possibility that this suppression was mediated through the decreased production of Th17 cells in the lung." (PMID 24959003, 2014). "HMGB1 acts on Alveolar epithelial type II cells (AT2) and plays a very important role in the regulation of chronic inflammation of the respiratory tract and remodeling in the mouse model of asthma caused by allergies." (PMID 40723867, 2025). "In the case of studies conducted on mouse asthma models, it has been shown that the use of HMGB1 neutralizing antibody reduces the production of Th1, Th2, and Th17 cells, which has a significant effect on the weakening of respiratory tract inflammation or mucus formation." (PMID 40723867, 2025). "The HMGB1/NLRP3 axis plays a pivotal role in asthma initiation and progression." (PMID 40688353, 2025). "And, in the study of asthma, HMGB1 has been demonstrated to induce Th17 cell differentiation by directly acting on naïve T cells to induce polarization and indirectly mediating the maturation and antigen‐presenting ability of dendritic cells to promote Th17 cell differentiation." (PMID 38414294, 2024). "Interestingly, murine asthma models have also demonstrated that blocking HMGB1 activity attenuates pathological airway changes, including airway inflammation and hyperresponsiveness." (PMID 39457624, 2024).